EIF5B (eukaryotic translation initiation factor 5B)
Description:
Plays a role in translation initiation. Ribosome-dependent GTPase that promotes the joining of the 60S ribosomal subunit to the pre-initiation complex to form the 80S initiation complex with the initiator methionine-tRNA in the P-site base paired to the start codon. Together with eIF1A (EIF1AX), actively orients the initiator methionine-tRNA in a conformation that allows 60S ribosomal subunit joining to form the 80S initiation complex. Is released after formation of the 80S initiation complex. Its GTPase activity is not essential for ribosomal subunits joining, but GTP hydrolysis is needed for eIF1A (EIF1AX) ejection quickly followed by EIF5B release to form elongation-competent ribosomes. In contrast to its procaryotic homolog, does not promote recruitment of Met-rRNA to the small ribosomal subunit.
Synonyms: IF2; KIAA0741; DKFZp434I036; FLJ10524
Tractability: Small molecule: a structure with a bound ligand is known. Antibody: the Human Protein Atlas places it where antibodies can reach. PROTAC: ubiquitination databases record sites on it; its protein half-life has been measured; a small molecule that binds it is known.
Target class: Enzyme; Hydrolase
Gene: Protein-coding gene on chromosome 2 (99,337,371 to 99,401,326, forward strand). Ensembl gene ENSG00000158417.
Subcellular location: Cytoplasm
Subcellular location (Human Protein Atlas): Cytosol; Plasma membrane
Pathways (Reactome):
Metabolism of proteins: GTP hydrolysis and joining of the 60S ribosomal subunit
Gene Ontology:
Molecular function: GTP binding; GTPase activity; protein binding; RNA binding; translation initiation factor activity; tRNA binding
Biological process: regulation of translational initiation; ribosome assembly; translational initiation
Cellular component: cytoplasm; nucleus; cytosol; synapse
Genetic constraint (gnomAD): Loss-of-function variants: 40 observed, 136.41 expected, observed/expected ratio (o/e) 0.29, 90% interval 0.23 to 0.38. The upper end of that interval is the gene's LOEUF score, 0.38, which puts it in group 1 of 6, group 1 being the genes least tolerant of losing a copy. Missense variants: 1,017 observed, 1,385.2 expected, observed/expected ratio (o/e) 0.73, 90% interval 0.7 to 0.77. Synonymous variants: 436 observed, 446.48 expected, observed/expected ratio (o/e) 0.98, 90% interval 0.9 to 1.06.
Homologues: Orthologues: chimpanzee EIF5B (99% identical), macaque EIF5B (99% identical), dog EIF5B (96% identical), rabbit EIF5B (94% identical), mouse Eif5b (91% identical), rat Eif5b (90% identical), pig EIF5B (88% identical), tropical clawed frog eif5b (77% identical), Caenorhabditis elegans F46B6.6 (14% identical), zebrafish eef2a.2 (5% identical), zebrafish eef2a.1 (5% identical). Paralogues in human: GSPT2 (13% identical), GSPT1 (13% identical), HBS1L (10% identical), EEF1A1 (9% identical), EEF1A2 (9% identical), MTIF2 (8% identical), GTPBP1 (8% identical), GTPBP2 (7% identical), EFL1 (7% identical), EFTUD2 (7% identical), EIF2S3 (6% identical), EIF2S3B (6% identical), and 6 more.
Diseases named in the same sentence as EIF5B in open-access papers:
EIF5B is named in the same sentence as 23 diseases in open-access papers, as found by Europe PMC text mining. Sharing a sentence is not in itself a finding about the gene and the disease. The quoted sentences say what the papers report.
glioblastoma (6 papers, 2018 to 2022). The most malignant astrocytic tumor (WHO grade IV). "eIF5B is overexpressed in a variety of malignancies, and the abnormal expression of eIF5B is associated with glioblastoma, lung cancer, and hepatocellular carcinoma." (PMID 36360287, 2022). "eIF5B is overexpressed in several malignancies and its aberrant expression has been linked to glioblastoma, lung carcinoma, and hepatocellular carcinoma." (PMID 34512736, 2021). "In glioblastoma cell lines, EIF5B suppressed apoptosis by promoting the translation of pro-survival and anti-apoptotic proteins." (PMID 37305324, 2022). "Translation of IRES-containing mRNAs, which encode anti-apoptotic proteins such as XIAP, Bcl-xL, and Cellular Inhibitor of Apoptosis Protein 1 (cIAP1) as well as Nuclear factor erythroid 2-related factor 2 (Nrf2), are regulated by eIF5B in glioblastoma multiforme (GBM) cells." (PMID 34512736, 2021). "Recently, eIF5B was shown to act as an essential factor for cap-dependent translation of hypoxia-response proteins in hypoxic glioblastoma (GBM) cells." (PMID 30670698, 2019). "Additionally, eIF5B was shown to act as an essential translation factor during hypoxia by facilitating Met-tRNAi delivery to ribosomes for efficient cap-dependent translation of hypoxia-response proteins in glioblastoma cells." (PMID 30551605, 2018). "Particularly, eIF5B, a subunit of eIF5, has been found to promote the translation of pro-survival and anti-apoptotic proteins in glioblastoma multiforme cell lines but has never been studied in prostate cancer." (PMID 34525951, 2021). "We have recently demonstrated a role for eIF5B in the non-canonical translation of several anti-apoptotic and pro-survival proteins involved in glioblastoma progression and resistance to therapeutic agents." (PMID 30551605, 2018).
hepatocellular carcinoma (5 papers, 2016 to 2022). A malignant tumor that arises from hepatocytes. "In this study, we investigated the functional role of eukaryotic initiation factor 5B (EIF5B) in hepatocellular carcinoma (HCC) and the underlying mechanisms." (PMID 37305324, 2022). "Furthermore, similar effects of eIF5B silencing on cellular processes were observed in both embryonic kidney cells and liver carcinoma cells in which eIF5B was knocked down." (PMID 27959964, 2016). "There is also growing evidence of high eIF5B expression levels in various malignancies like GBM, lung adenocarcinoma (LUAD) and hepatocellular carcinoma (HCC), signifying the importance of eIF5B as the stress-related tumorigenic eIF." (PMID 34512736, 2021).
viral infection (5 papers, 2018 to 2025). "The resulting C-terminal fragment of eIF5B can substitute eIF2 as an initiation factor to deliver Met-tRNAimet to the 40S ribosome while eIF2-α is phosphorylated during a viral infection." (PMID 29971060, 2018). "In addition to cleaving the viral polyprotein, the 3Cpro protein of PV has been reported to cleave eIF5B during a viral infection." (PMID 29971060, 2018). "To test the impact of eIF5B knock-down on cell viability and the rate of MG1 infection, we used the live-cell imaging to monitor the rate of cell survival and MG1 infection in the eIF5B-depleted and control cells during the viral infection." (PMID 30700020, 2019). "These operations involve tasks beyond large subunit recruitment, as it has been demonstrated that eIF5B exerts a critical role in initiation AUG codon selection accuracy or Met-tRNAiMet delivery in noncanonical scenarios like viral infection or cellular stress." (PMID 31900355, 2020).
enterovirus infection (3 papers, 2015 to 2024). "Published studies on poliovirus have also demonstrated that resistance to eIF2α phosphorylation increases as enteroviral infection progresses due to the cleavage of initiation factor eIF5B by the viral 3C protease." (PMID 25747578, 2015). "Moreover, upregulation of eIF5B controls cell-cycle arrest and specific developmental stages, and eIF5B cleavage has been identified in enterovirus infection." (PMID 27959964, 2016).
glioma (3 papers, 2019 to 2023). A benign or malignant brain and spinal cord tumor that arises from glial cells (astrocytes, oligodendrocytes, ependymal cells). "So far, the involvement of eIF5B in gliomas has only been studied in the context of IRES-dependent translation and will therefore be discussed in the cap-independent section." (PMID 31795417, 2019). "eIF5B is often overexpressed in cancer which is in agreement with our REMBRANDT data analysis showing that EIF5B is overexpressed in gliomas." (PMID 31795417, 2019). "Finally, we have analyzed EIF5 and EIF5B expression in gliomas and found that EIF5 is downregulated in astrocytomas and in GBM, only for the mesenchymal and proneural subtypes." (PMID 31795417, 2019). "Overcoming therapy resistance also involves TRAIL resistance of glioma tumor cells, and progress has been made even in this regard by sensitizing tumor cells to TRAIL-induced apoptosis through inhibition of KDM2B and eIF5B." (PMID 37626776, 2023).
lung adenocarcinoma (3 papers, 2021 to 2025). A carcinoma that arises from the lung and is characterized by the presence of malignant glandular epithelial cells. "Some studies have demonstrated that overexpression of EIF5B might induce PD-L1-related signaling pathways, which are frequent in lung adenocarcinomas and highly associated with a poor prognosis." (PMID 36861063, 2023).
bladder cancer (2 papers, 2020 to 2024). "The role of EIF5B in bladder cancer was unknown, but it was reported as an antagonist of the G0 phase." (PMID 32640634, 2020).
breast carcinoma (1 paper, 2024). "One of the first interactions that emerged in breast cancer tissue compared to normal tissue was the interaction between RMND5A, EIF5B, SUN2, KLHL18, KDSR, RPSK6KA3 ceRNAs and the miR-338-5p, miR-223-3p, miR-129-5p, miR-642a-5p, miR-3619-5p, and miR-382-5p miRNAs." (PMID 38627780, 2024).
colon cancer (1 paper, 2022). "More recently, CRISPR‒Cas9-based screenings in lung and colon cancer cell lines identified eukaryotic translation initiation factor 5B (eIF5B) and myeloid/lymphoid or mixed-lineage leukemia, translocated to 6 (MLLT6) as novel regulators of PD-L1 abundance, respectively." (PMID 36357569, 2022).
female sterility (1 paper, 2016). "eIF5B interacts with DEAD-box RNA helicase Vasa (Vas), with reduction of Vas-eIF5B interaction in Drosophila causing female sterility, reduced Gurken (Grk) protein levels, nearly complete loss of germ cell formation, and reduction of somatic posterior patterning." (PMID 28083147, 2016).
lewis lung carcinoma (1 paper, 2021). "Depletion of eIF5B reduced tumor mass and propagation in lewis lung carcinoma (LLC) and non-small cell lung cancer (NSLC) cell lines, respectively, demonstrating the dependence of cancer cells on eIF5B for growth and proliferation." (PMID 34512736, 2021). "Similarly, knocking down eIF5B decreased the levels of programmed death-ligand 1 (PD-L1) in heme starved non-small cell lung cancer (NSLC) and lewis lung carcinoma (LLC) cells." (PMID 34512736, 2021).
osteoporosis (1 paper, 2022). A condition of reduced bone mass, with decreased cortical thickness and a decrease in the number and size of the trabeculae of cancellous bone (but normal chemical composition), resulting in increased fracture incidence. "According to previous study, EIF5B and HSP90B1 have also not been reported in osteoporosis." (PMID 35859791, 2022).
prostate carcinoma (1 paper, 2021). A carcinoma that arises from epithelial cells of the prostate gland. "To investigate the effect of eIF5B on the killing capability of immune cells, we isolated PBMCs from the peripheral blood of healthy people and co-cultured them with the transfected prostate cancer cells." (PMID 34525951, 2021). "To verify the effect of eIF5B on prostate cancer cells, we transfected eIF5B shRNA and its control into PC-3 and VCaP." (PMID 34525951, 2021). "In this study, we found compared with normal prostate epithelial cells, the expression of eIF5B and PD-L1 were significantly up-regulated in prostate cancer cells." (PMID 34525951, 2021). "Interference of eIF5B expression can inhibit the proliferation, migration, invasion, and immunosuppressive response of prostate cancer cells, as well as tumor growth." (PMID 34525951, 2021). "Western blot was used to detect the protein expressions of eIF5B and PD-L1 in human normal prostate epithelial cells and prostate cancer cells." (PMID 34525951, 2021). "Secondly, the regulatory effects of eIF5B on the expression of PD-L1 in prostate cancer cells have only been confirmed at the cellular level, and further verification at the clinical level is needed for greater clinical significance." (PMID 34525951, 2021). "Compared with normal prostate epithelial cells, prostate cancer cells revealed higher expressions of eIF5B and PD-L1 interference with eIF-5B expression can inhibit the proliferation, migration, invasion and PD-L1 expression of prostate cancer cells." (PMID 34525951, 2021). "To explore the regulatory correlation between eIF5B and PD-L1 in prostate cancer cells, we detected the expression levels of PD-L1 mRNA and PD-L1 protein in PC-3 and VCaP cell lines after interference with eIF5B expression by qRT-PCR and Western blot." (PMID 34525951, 2021). "Judging from the results, the expressions of PD-L1, both its mRNA and protein, were significantly inhibited in the eIF5B siRNA groups (P<0.01), suggesting that interference with eIF5B expression could inhibit PD-L1 expression in prostate cancer cells." (PMID 34525951, 2021). "CoIP assays showed that Wig1 could bind to eIF5B in prostate cancer cells, and its overexpression can inhibit the proliferation, migration, invasion and PD-L1 expression of cancer cells while promoting apoptosis." (PMID 34525951, 2021). "Interfering the expression of eIF5B could inhibit the proliferation of prostate cancer cells and PD-L1 expression, thereby enhancing the killing capability of PBMCs on prostate cancer cells." (PMID 34525951, 2021). "Following that, the present study will investigate whether eIF5B affects PD-L1 expression in prostate cancer cells by interacting with Wig1." (PMID 34525951, 2021). "In a word, our results suggest that interference with eIF5B expression could inhibit the proliferation, migration and invasion of prostate cancer cells, while promoting their apoptosis." (PMID 34525951, 2021). "This study proposes a new target, eIF5B, for immunotherapy of prostate cancer." (PMID 34525951, 2021). "Besides, interference with eIF5B expression can inhibit the proliferation, migration, invasion and immunosuppressive response of prostate cancer cells." (PMID 34525951, 2021). "However, the effect of eIF5B on immunosuppression in prostate cancer has not been studied yet." (PMID 34525951, 2021).
stomach adenocarcinoma (1 paper, 2017). "Further analysis revealed an unexpected enrichment of NMD-elicit mutations in LARP4B (22/54 compared) and EIF5B (12/54) in hypermutated stomach adenocarcinoma cases." (PMID 28649990, 2017).
T-cell lymphoma (1 paper, 2023). "The best-known eIF2-less mechanisms replace eIF2 with eIF5B or MCT-1•DENR (multiple copies in T-cell lymphoma • density regulated protein complex)." (PMID 36689548, 2023).
cancer (11 papers, 2015 to 2025). A tumor composed of atypical neoplastic, often pleomorphic cells that invade other tissues. "It is conceivable that NMD-mediated hypofunction of LARP4B or EIF5B permits the hypermutated cancer cells to cope with a high mutation load by delaying translation." (PMID 28649990, 2017). "The transcript levels, copy number, and protein levels of EIF5B were significantly increased in the HCC tissues compared with the non-cancer liver tissues." (PMID 37305324, 2022). "With Wig1 overexpression, PD-L1 dropped and cancer cell apoptosis was promoted, suggesting that eIF5B regulates PD-L1 expression indirectly through Wig1." (PMID 34525951, 2021). "Numerous uORF dependent proteins have been identified whose expression is regulated by eIF5B, and many of these proteins have implications in cancer resistance and cell cycle." (PMID 34512736, 2021). "This review recapitulates eIF5B’s regulatory roles in the translation initiation of viral mRNA as well as the cellular mRNAs in cancer and stressed eukaryotic cells." (PMID 34512736, 2021). "Considering its pivotal role in cancer cells, eIF5B is emerging as a therapeutic target for cancer treatment." (PMID 34512736, 2021). "eIF5B enhances the expression of these survival proteins to allow cancer cells to metastasize and resist chemotherapy." (PMID 34512736, 2021). "Previous studies suggest eIF5B mediates the IRES containing subset of mRNA translation to resist apoptosis in cancer cells." (PMID 34512736, 2021). "Compared to those in the NC siRNA groups, cancer cells in the eIF5B siRNA groups demonstrated significantly lower capabilities of proliferation, migration, and invasion." (PMID 34525951, 2021). "On the other hand, in eIF5B shRNA groups, the proportion of apoptotic cancer cells rose significantly, but PD-L1 expression dropped as well (P < 0.01)." (PMID 34525951, 2021). "For example, a small molecule denoted LWW31 was suggested to inhibit eIF5B activity and lower the viability of cancer cells." (PMID 34512736, 2021). "These promising works highlight that further research is required to screen and identify clinically relevant small molecules and peptides for targeting eIF5B in “hard-to-treat” and “high-fatality” cancers such as GBM." (PMID 34512736, 2021). "Meanwhile, the cancer cell group with interference with eIF5B expression also demonstrated greater, apoptosis and higher vulnerability to PBMCs." (PMID 34525951, 2021). "Taken together, the data suggest that those cancers which rely most heavily on the cap-independent translation of pro-survival proteins will be most affected by targeting eIF5B." (PMID 30670698, 2019). "Taken together, our data suggest that eIF5B represents a regulatory node, allowing cancer cells to evade apoptosis by promoting the translation of pro-survival proteins from IRES-containing mRNAs." (PMID 30670698, 2019). "Given that eIF5B positively regulates such a wide variety of pro-survival proteins and is largely dispensable under normal growth conditions 19, we suggest that eIF5B represents a novel target to sensitize difficult-to-treat cancers to pro-apoptotic stimuli." (PMID 30670698, 2019). "Of note, the majority of the surveyed cancers show reduced eIF5B staining, when compared to the expression of eIF5B in normal tissues, suggesting that a relationship between eIF5B and tumorigenesis is likely not straightforward." (PMID 26636041, 2015). "Several studies have reported that EIF5B functions as an oncogene and promotes cancer progression." (PMID 37305324, 2022). "Additionally, fundamental biomedical and pre-clinical studies are necessary to establish eIF5B as a therapeutic target for cancer treatments." (PMID 34512736, 2021). "Cancers with upregulated eIF5B have been challenging to treat, and this could change if druggability of eIF5B is further explored as it is a viable therapeutic target." (PMID 34512736, 2021).
cancer (continued). "Besides, with crystal violet staining and flow cytometry, we also found that the numbers of living cancer cells in eIF5B shRNA groups were significantly lower than those in groups without shRNA or those with shRNA and PD-L1 overexpression." (PMID 34525951, 2021). "We thus sought to determine whether eIF5B has a role in the viability of cancer cells." (PMID 30670698, 2019). "Transwell assay results showed that EIF5B silencing decreased the migration of HCC cells by suppressing EMT and decreasing the expression levels of MMP-2 and MMP-9, which are required for cancer progression." (PMID 37305324, 2022). "Thus, regulating eIF5B could impact such pathways necessary for cancer survival." (PMID 34512736, 2021). "Furthermore, EIF5B knockdown suppressed epithelial-mesenchymal transition (EMT) and the cancer stem cell (CSC) phenotype." (PMID 37305324, 2022). "UALCAN database analysis demonstrated that the EIF5B transcript levels were significantly higher in the tumor tissues from multiple cancers including HCC compared to the corresponding non-cancer tissues (p < 0.05)." (PMID 37305324, 2022). "We further discuss how eIF5B acts as a nexus between non-canonical translation and the survival of cancer cells." (PMID 34512736, 2021). "However, a precise role of eIF5B in cancer progression has not been defined." (PMID 30670698, 2019). "Nevertheless, other four cancer-related candidate proteins (KI67, NUMA1, EIF5B and PRRC2C) could not be validated in cells." (PMID 37072811, 2023).